MTHFD1 (methylenetetrahydrofolate dehydrogenase, cyclohydrolase and formyltetrahydrofolate synthetase 1)
Diseases named in the same sentence as MTHFD1 in open-access papers (continued):
Sharing a sentence is not in itself a finding about the gene and the disease.
cancer (continued). "We here propose that MTHFD2 supports formate overflow in cancer cells rendering them sensitive to MTHFD1(DC) inhibition by TH9619." (PMID 37012496, 2023). "For example, any drug targeting mitochondrial methylenetetrahydrofolate dehydrogenase (MTHFD1L) cancer cells can compensate using cytoplasmic MTHFD1." (PMID 37627515, 2023). "On the other hand, the MTHFD1 1958GG genotype, more frequent among cancer patients, indicates a trend towards global PBMCs DNA hypomethylation as commonly observed in cancer." (PMID 28968444, 2017). "Then mCyt levels were analysed according to MTHFD1 1958G>A genotypes in the three different type of cancer." (PMID 28968444, 2017). "The MTHFD1 1958G>A genotype frequencies were then analysed according to the different types of cancer." (PMID 28968444, 2017). "MTHFD1 has three distinct enzymatic activities (5,10-methylenetetrahydrofolate dehydrogenase, 5,10-methenyltetrahydrofolate cyclohydrolase, 10-formyltetrahydrofolate synthetase), which played a significant role in the development of different types of cancers." (PMID 39857769, 2025). "LGALS4 may play a critical role in tumor-specific pathways, while MTHFD1 may be involved in both cancer cell proliferation and microenvironmental interactions." (PMID 39857769, 2025). "Toxicity to non-cancer cells due to the inhibition of MTHFD1 will, however, remain a major issue." (PMID 41303507, 2025). "LGALS4’s association with malignant cells may reflect its role in tumor-specific pathways, while MTHFD1’s broader expression suggests its involvement in both cancer cell proliferation and microenvironmental interactions." (PMID 39857769, 2025). "MTHFD1 was identified as a novel suppressor of anoikis and facilitated cancer metastasis." (PMID 39148981, 2024). "Furthermore, miR-197-3p directly regulates other genes implicated in trastuzumab resistance, including FOXJ2, MTHFD1, RAN, TUSC2, and FUS1, though their specific roles in drug resistance and cancer progression require further investigation." (PMID 38534787, 2024). "Our data provide a rationale for future studies focusing on MTHFD1/2 inhibitors and whether they may selectively sensitize cancer cells during radiotherapy." (PMID 38533616, 2024). "Cancer cells fuel their increased need for nucleotide supply by upregulating one-carbon (1C) metabolism, including the enzymes methylenetetrahydrofolate dehydrogenase–cyclohydrolase 1 and 2 (MTHFD1 and MTHFD2)." (PMID 37012496, 2023). "The serine synthesis pathway is catalysed by several enzymes, such as PHGDH, SHMT1/2, and MTHFD1/2, and their suppression may decrease cancer cell growth and survival." (PMID 37664062, 2023). "Moreover, available information suggests that several other TRAF3-regulated metabolic enzymes (e. g., Lpcat1, Pygl, Hk2, and Mthfd1) are also targetable points in cancers." (PMID 36776285, 2023). "Instead, we show that TH9619 targets MTHFD2-expressing cancer cells by inhibiting MTHFD1(DC)." (PMID 37012496, 2023). "Moreover, the folate trapping mechanism now provides an incentive for developing MTHFD1(DC)-specific inhibitors to treat MTHFD2-expressing cancers." (PMID 37012496, 2023). "Interestingly, the present study showed a significantly different distribution of the MTHFD1 1958G>A genotypes between cancer and cancer-free subjects." (PMID 28968444, 2017). "Our meta-analysis suggests that the MTHFD1 G1958A polymorphism might be associated with a decreased a decreased risk of ALL and other cancers." (PMID 23894459, 2013). "In this meta-analysis, when stratifying by ethnicity we found that the association between MTHFD1 G1958A polymorphism a decreased risk of cancer was significant only in Asians, not in the Caucasian population." (PMID 23894459, 2013). "The results suggest that MTHFD1 G1958A polymorphism might be associated with a decreased risk of ALL and other cancers." (PMID 23894459, 2013).
cancer (continued). "The results indicate that MTHFD1 G1958A and G401A are not risk factors for developing cancer in the overall study populations." (PMID 23894459, 2013). "Moreover, the present results suggest that both MTHFD1 1958AA and 1958GA genotypes could be protective for cancer through modulation of DNA methylation." (PMID 28968444, 2017). "The MTHFD1 1958G>A variants have been mainly studied in relation to neural tube defects and embryonic development, but it has been also described as associated to cancer disease, although with not univocal results." (PMID 28968444, 2017). "In support of this notion, growing evidence has revealed that MTHFD1 and MTHFD2 levels are notably upregulated and correlated with poor prognosis across various cancer types." (PMID 38723197, 2024). "TH9619 is a potent inhibitor of dehydrogenase and cyclohydrolase activities in both MTHFD1 and MTHFD2, and selectively kills cancer cells." (PMID 37012496, 2023). "This study discovered that drugs targeting MTHFD1 can kill cancer cells that have upregulated MTHFD2, revealing cancer vulnerabilities that can be exploited for drug development." (PMID 37012496, 2023). "Genotyping for BHMT 716A>G, DHFR 19bp ins/del, MTHFD1 1958G>A, MTHFR 677C>T, MTR 2756A>G, MTRR 66A>G, RFC1 80G>A, SHMT1 1420C>T, TCII 776C>G and TS 2rpt-3rpt was performed in 102 cancer patients and 363 cancer-free subjects." (PMID 28968444, 2017). "We show that the human FolD orthologs, MTHFD1 and MTHFD2, are also inhibited in the low nM range, and that micromolar concentrations of carolacton inhibit the growth of cancer cell lines." (PMID 29142318, 2017). "Thus, beyond the blockage of cancer-enriched MTHFD2, this drug will also inhibit the essential MTHFD1." (PMID 41303507, 2025). "Challengingly, they also demonstrated strong inhibition of the MTHFD1 and MTHFD2L isoforms, which are expressed in healthy adult human tissues, unlike MTHFD2 that is explicitly expressed in several cancer cells." (PMID 39256448, 2024). "Intriguingly, the expression of SHMT1, MTHFD1, and ALDH1L1 had no influence on the survival rate of patients with CRC and LA, suggesting it is not the folate metabolism per se but the THF cycle in the mitochondria that confers poor prognosis in cancers." (PMID 29321536, 2018).
tumor (27 papers, 2008 to 2025). "The TIDE (tumor immune dysfunction and exclusion) analysis revealed a strong association of MTHFD1 and LGALS4 expression with immunotherapy outcomes in PRAD." (PMID 39857769, 2025). "MTX is the inhibitor of folic acid metabolism, which can cause the loss of chromatin-associated MTHFD1, but the anti-tumor effect of MTX alone in NB seems unsatisfactory due to high toxicity and side effects." (PMID 38336749, 2024). "scRNA-seq showed that MTHFD1 was specifically distributed in tumor-associated macrophages (TAMs), mediating the differentiation and immunosuppressive functions of macrophages, which may potentially impact endothelial cell proliferation and tumor angiogenesis." (PMID 38730286, 2024). "In contrast, high expression of MTHFD1 was associated with lower TIDE scores (p < 0.01), suggesting a different role in the tumor microenvironment." (PMID 39857769, 2025). "Genetic knockdown of MTHFD1 or application of folic acid inhibitor MTX combined with JQ1 can synergistically inhibit tumor progression in MYCN-amplified NB." (PMID 38336749, 2024). "In conclusion, this study revealed the tumor-promoting role of MTHFD1 in NB, and elucidated the molecular mechanism by which MTHFD1 was directly transcriptionally regulated by MYCN." (PMID 38336749, 2024). "The results of RT-qPCR on 21 fresh tumor tissue samples of NB patients from our center further indicated a positive correlation between MTHFD1 and MYCN at the transcriptional level (R2 = 0.6690, P < 0.0001)." (PMID 38336749, 2024). "Hematoxylin and eosin (H&E) staining analysis revealed a lower rate of lung metastasis and fewer tumor metastatic nodules in nude mice with MTHFD1 knockdown compared to the control group." (PMID 39571599, 2024). "MTHFD1 is reported to be a potential oncogene in tumorigenesis, with a high expression in tumor cells." (PMID 38730286, 2024). "The PRMT5/MTHFD1 axis promotes tumor resistance and accelerates its metastasis in oesophageal squamous cell carcinoma." (PMID 38226966, 2024). "In this study, it was found that MTHFD1 played a tumor-promoting role in MYCN-amplified NB, and it promoted proliferation and migration but inhibited apoptosis of NB cells." (PMID 38336749, 2024). "In the folate cycle, SLC19A1 and MTHFD1 had upregulated expression in 6, 6 tumors and downregulated expression in 3, 1 tumor, respectively." (PMID 31828117, 2019). "MTHFD1 maintains redox homeostasis and protects tumor cells from oxidative stress." (PMID 38336749, 2024). "Inhibition of MTHFD1 augments the anti-tumor effect of JQ1 in MYCN-amplified NB." (PMID 38336749, 2024). "Moreover, genetic knockdown of MTHFD1 or application of the anti-folic acid metabolism drug methotrexate (MTX) potentiated the anti-tumor effect of JQ1 both in vitro and in vivo." (PMID 38336749, 2024). "The average tumor weights of the knockdown of MTHFD1 were 450 mg, and it was 178 mg in controls." (PMID 39571599, 2024). "In the context of LUAD, MTHFD1 could influence tumor progression through effects on DNA synthesis and methylation, potentially affecting cell proliferation and survival." (PMID 38596689, 2024). "The results suggested that MTHFD1 maintained redox homeostasis in MYCN-amplified NB, and inhibiting MTHFD1 in tumor cells may weaken the resistance to oxidative stress, thus preventing the malignant progression of tumors." (PMID 38336749, 2024). "Moreover, tumor weight in shNC group was larger than that in the other two groups, suggesting an anti-proliferation effect of MTHFD1 knockdown." (PMID 38336749, 2024). "Furthermore, the role of MTHFD1 was evaluated in vivo by using subcutaneous xenograft tumor models and lateral tail vein metastasis models of human CRC in nude mice." (PMID 39571599, 2024). "In addition, mast cells and macrophages play a key role in immune escape from tumors; MTHFD1 may alter the immune response in the tumor microenvironment by modulating the metabolism of these immune cells." (PMID 39857769, 2025).
tumor (continued). "Excessive expression and activity of MTHFD1 may sustain high proliferative capacity of tumor cell, enhance invasive and metastatic capabilities, influence apoptosis and cell cycle regulation pathways, and be associated with poor prognosis and increased risk of recurrence in tumors." (PMID 38730286, 2024). "This analysis confirmed the association of TYMS, TK1, SHMT2, MTHFD2, and DHFR expressions with the main prognosis markers (hypermutation, MSI, iCluster, expression subtype, and tumour stage) while MTHFD1, and not MTHFD2, was more strongly associated with methylation status." (PMID 38540202, 2024). "Therefore, MTHFD1 inhibition may increase the sensitivity of PCa cells to chemotherapeutic agents, such as docetaxel, by disrupting the nucleotide and amino acid pathways essential for tumor growth." (PMID 39857769, 2025). "Targeting both MTHFD1 and the PI3K‐AKT‐mTOR signaling pathway concurrently represents a promising strategy for inhibiting tumor growth and metastasis." (PMID 39571599, 2024). "Our results indicated significant overexpression of GALNT2, MTHFD1, FAM207A, KRT81, and IKZF3 in tumor tissues, consistent with our bioinformatics analysis." (PMID 38596689, 2024). "It was worth noting that, the P value between MTHFD1 expression and MYCN status was 0.058 in our observation, which ought to be verified with a larger sample size of tumor tissues." (PMID 38336749, 2024). "Correlation analysis verified a positive association between MTHFD1 expression and CCL18+ immunosuppressive macrophages, collectively indicating that increased level of MTHFD1 may be associated with the polarization and immunosuppressive functions of macrophage in the tumor microenvironment." (PMID 38730286, 2024). "This metabolism enrichment highlighted enzymes at the interface between glycolysis (GAPDH, ENO1, LDHA) and one-carbon metabolism (TYMS, SHMT2, MTHFR, MTHFD1), further confirming the importance of these two pathways in CIMP tumours." (PMID 38540202, 2024). "The expression levels of four genes, HIF1A, MTHFD1, GGH and TYMS, in tumor tissues can predict the response to preoperative CRT including either S-1 or UFT/LV." (PMID 28417167, 2017). "The expression levels of four genes (HIF1A, MTHFD1, GGH and TYMS) in tumor tissue before CRT can predict the response to preoperative CRT including S-1 or UFT/LV." (PMID 28417167, 2017). "The results revealed that MTHFD2, but not MTHFD1, was overexpressed in tumor tissues vs. matched paracancerous tissues." (PMID 38723197, 2024). "By comparing tumor versus non-transgenic tissue the genes Mthfd1, Myom1 and Ppp2r5c showed change in direction of gene expression." (PMID 22815814, 2012). "As a result of tumor immunity analysis, MTHFD2L expression was found to be negatively related to the Estimate-Stromal-Immune score in OSCC; however, there was no statistical significance between the Estimate-Stromal-Immune score and MTHFD1, MTHFD1L, or MTHFD2 in OSCC." (PMID 35693982, 2022). "However, when comparing tumor versus transgenic tissue gene Kif26b showed a change in direction and when comparing tumor versus non-transgenic tissue the genes Mthfd1, Myom1 and Ppp2r5c equally differed in direction of gene expression." (PMID 22815814, 2012). "FatiGO+ analysis showed that tumor libraries had significantly more expressed genes related to "cell organization and biogenesis" (GO:0016043), KRT7, PDIA3, PPGB and TRAPPC5 (p = 0.005); and "ligase activity" (GO:0016874), UBE2S and MTHFD1 (p = 0.028) than normal libraries." (PMID 18302799, 2008). "However, there was no statistical significance between MTHFD1, MTHFD1L, or MTHFD2 and the tumor microenvironment in OSCC." (PMID 35693982, 2022).
MTHFD1 also shares sentences with these, for which no sentence is quoted: Down syndrome (2 papers); hyperhomocysteinemia (2); Hypertension (2); leukemia (2); lung squamous cell carcinoma (2); adenocarcinoma (1); atrial septal defect (1); bladder urothelial carcinoma (1); cleft palate (1); colonic adenoma (1); COVID-19 (1); dementia (1); Depression (1); diabetes mellitus (1); epilepsy (1); head and neck cancer (1); Heart Disease (1); infection (1); intrauterine growth restriction (1); lymph node metastasis (1); malignant pleural mesothelioma (1); megaloblastic anemia (1); MERRF syndrome (1); metabolic disorder (1); migraine (1); nasopharyngeal carcinoma (1); oral squamous cell carcinoma (1); prediabetes (1); Progressive myoclonic epilepsy (1); small cell lung carcinoma (1).
A further 3 diseases each share a sentence with MTHFD1 in 1 paper.